IFI44 (interferon induced protein 44)
Description:
This protein aggregates to form microtubular structures.
Synonyms: p44; MTAP44; TLDC5
Tractability: PROTAC: ubiquitination databases record sites on it; its protein half-life has been measured.
Gene: Protein-coding gene on chromosome 1 (78,647,078 to 78,664,412, forward strand). Ensembl gene ENSG00000137965.
Subcellular location: Cytoplasm
Subcellular location (Human Protein Atlas): Nucleoplasm
Pathways (Reactome):
Immune System: Modulation of host responses by IFN-stimulated genes
Gene Ontology:
Molecular function: protein binding
Biological process: immune response; response to virus
Cellular component: cytosol; cytoplasm
Genetic constraint (gnomAD): Loss-of-function variants: 31 observed, 35.15 expected, observed/expected ratio (o/e) 0.88, 90% interval 0.66 to 1.19. The upper end of that interval is the gene's LOEUF score, 1.19, which puts it in group 5 of 6, group 1 being the genes least tolerant of losing a copy. Missense variants: 564 observed, 493.08 expected, observed/expected ratio (o/e) 1.14, 90% interval 1.07 to 1.23. Synonymous variants: 195 observed, 181.13 expected, observed/expected ratio (o/e) 1.08, 90% interval 0.96 to 1.21.
Homologues: Orthologues: chimpanzee IFI44 (98% identical), macaque IFI44 (85% identical), pig IFI44 (59% identical), dog IFI44 (57% identical), rabbit IFI44 (57% identical), mouse Ifi44 (54% identical), rat Ifi44 (52% identical), zebrafish ifi44c1 (35% identical), zebrafish si:ch211-197g15.5 (34% identical), zebrafish si:ch211-197g15.9 (34% identical), zebrafish ifi44c2 (34% identical), zebrafish ifi44f4 (33% identical), and 11 more. Paralogues in human: IFI44L (44% identical).
Diseases named in the same sentence as IFI44 in open-access papers:
IFI44 is named in the same sentence as 99 diseases in open-access papers, as found by Europe PMC text mining. Sharing a sentence is not in itself a finding about the gene and the disease. The quoted sentences say what the papers report.
viral infection (45 papers, 2012 to 2026). "Our results show that inhibition of the IFI44 gene mitigated necrosis induced by Poly(I:C), thereby alleviating the excessive inflammatory response and tissue damage associated with viral infection." (PMID 40390102, 2025). "IFI44, was associated with multiple different viral infections, and has been shown to induce an antiproliferative state in cells." (PMID 32793510, 2020). "It has already been implicated in host response to viral infections, as it was shown that IFI44 silencing inhibits the replication of multiple viruses, whereas its overexpression inhibits the antiviral response due to negative regulation of the interferon pathway mediated by IRF-3 and NF-κB." (PMID 39859996, 2025). "IFN-induced protein 44 (IFI44) is linked to various viral infections." (PMID 36567857, 2022). "Remarkably, these new IFI44 functions may have implications for diseases associated with excessive immune signaling and for controlling virus infections mediated by IFN responses." (PMID 31455651, 2019). "IFI44 is an IFNα-inducible protein that is associated with several viral infections, but its role in bacterial infections is unknown." (PMID 31886294, 2019). "The sGenes found within this gene set include MX1, HLA-C, and IFI44, which play important roles in host response specifically to viral infections." (PMID 41542048, 2026). "Although OAS1Z and IFI44 are recognized for their roles in viral infections, they can also be induced in response to certain parasites." (PMID 38543637, 2024). "IFI44 is an interferon-a inducible protein which suppresses the immune response during viral infection." (PMID 39001376, 2024). "IFI44 is a type I IFN induction protein that has been shown to be upregulated in different viral infections and immune-related diseases." (PMID 37898694, 2023). "Five hub genes shared by RA, COVID-19, and SAB were IFI44, OAS1, IFI44L, ISG15, and HERC5, and they were found to be closely associated with the immune system response to viral infection and bacterial infection using Metascape analysis." (PMID 36189314, 2022). "Although most ISGs encode proteins capable of inhibiting different stages of the SARS-CoV-2 replication cycle, a few ISGs, including SOCS, USP18, and IFI44, can promote viral infection of the host." (PMID 36189314, 2022). "IFI44L is a paralog gene of IFI44 and functions as a regulator of cell apoptosis, virus infection, and congenital immune response." (PMID 35620480, 2022). "Studies have shown that IFI44 is a potential inflammatory factor and can defend against viral infection through the inhibition of viral transcription." (PMID 33468223, 2021). "This study is important because IFI44 and IFI44L are upregulated after a wide range of viral infections, and IFI44L can serve as a diagnostic biomarker of viral infection." (PMID 32611756, 2020). "Recently, the IFN-induced protein 44 (IFI44) was found to negatively modulate the NF-κB activity induced after viral infections." (PMID 32580383, 2020). "In this work, we describe a completely novel function for IFI44 in negatively modulating the innate immune responses induced after viral infections." (PMID 31455651, 2019). "As expected, after viral infections, high levels of IFI44 and of IFN-induced protein with tetratricopeptide repeats 2 (IFIT2) (an ISG) were induced." (PMID 31455651, 2019). "It is well known that type-I IFN induces potent cellular defense against viral infection mediated by up-regulation of ISGs like IFI44, IFI44L, and HERC5." (PMID 31749827, 2019). "To analyze the effect of IFI44 in conferring biologically relevant IFN-mediated antiviral activity to virus infection, we assessed the effect of IFI44 downregulation (siRNA transfection) or overexpression (plasmid transfection) on viral infection." (PMID 31455651, 2019). "IFI44L is a paralog of IFI44, a well-known immune response gene induced in response to viral infections." (PMID 30296270, 2018).
viral infection (continued). "In contrast, GW3965 significantly enhanced dexamethasone-induced mRNA expression of the interferon-induced protein 44 (Ifi44) and the 2′-5′ oligoadenylate synthetase 1A (Oas1a), both of which play key roles in innate immune responses against viral infections." (PMID 22457708, 2012). "Functional validation studies reveal that the IFI44 gene acts as a negative regulator of the antiviral response; its inhibition effect significantly reduced Poly(I:C)-induced cell necrosis, while enhancing apoptosis to combat viral infections." (PMID 40390102, 2025). "Similarly to the OAS family, Ifi44 is one of the first ISGs after viral infections to stimulate PPRs." (PMID 37111215, 2023). "The function and pathway enrichment analyses of M. tuberculosis H37Rv-infected macrophage by RNA-seq demonstrated that gene enrichment was closely associated with viral infection genes, including TRIM22, IFIT1, IFI44L, and IFI44, consistent with M. tuberculosis being an intracellular pathogen." (PMID 34722780, 2021). "In our analysis, we have observed that XAF1 and IFI44 protein in virus-infected cells, which could be targeted against viral infection." (PMID 32566414, 2020). "Future works must therefore focus on the IFIT1–3 and IFI44 proteins, as well as on other yet identified proteins that induce chronic innate immune activation after viral infection and on the possibility that viral remnants contained in macrophages or other cell types, drive this process." (PMID 33081322, 2020). "Interestingly, the levels of IFIT2 induction measured after the virus infections were 2.5-fold to 6-fold higher in the IFI44-silenced cells than in the NT-silenced control cells." (PMID 31455651, 2019). "In addition, dozens ISGs, among which some have been characterized for their antiviral activities against various other viral infections, for example Mx1, Ifit1, Isg15, Ifi44, Ddx60, Oasl and Irf7 were up-regulated upon HDV inoculation in hNTCP-Tg mice." (PMID 25902143, 2015). "Thus, the association of IRF-1, IFI-44, Mx1, OAS2, and HSH2D with HLA-DR could suggest a possible relationship between viral infection and HLA-DR expression." (PMID 30374345, 2018). "The induction of OAS1, OAS2, and OASL, which, as main sensors for viral infections, explains the induction of numerous interferon-induced proteins (e.g., IFIT1, IFIT2, IFI44, MX1, MX2)." (PMID 39062793, 2024). "IFI44 is a cytoplasmic protein and a type I IFN-induced protein and is upregulated upon a variety of virus infections." (PMID 32566414, 2020). "Then, the expression of IFI44-HA, FKBP5-FLAG, actin (as a control), and the viral nucleoprotein (NP) (as a marker of viral infection) was analyzed by Western blotting." (PMID 31455651, 2019). "Unlike for Atlantic salmon, for which none of the biomarkers showed particular discrimination between viral disease and BKD, in Chinook salmon, five biomarkers—UBL1 (PSMP2), LGAL3BP (GAL3), IFI44 (both A and C paralogs) and PSMB8—were discriminatory." (PMID 28702195, 2017). "The antiviral-ISG, including GBP1, IFI44, IFIH1, IFIT1, MX1, and LY6E, were the most common group of up-regulated genes after influenza infection, yellow fever vaccination, and during febrile episodes of dengue hemorrhagic fever." (PMID 24069471, 2013). "Up-regulated differentially expressed genes (DEGs) indicated a clear relationship with the innate immune response against viral infection, including genes coding PRRs (LPG2 or DHX58) and IFN-stimulated genes (ISG15, Mx, STAT1, HERC5, IFI44, IFIT-1, NUP133, TRIM21)." (PMID 35215144, 2022). "The data presented here explore how the ISGs IFI44 and IFI44L modulate viral infection." (PMID 32611756, 2020). "Regarding upregulated DEGs, a clear relationship with the innate immune response against viral infection was observed, being unigenes detected those coding pattern recognition receptors (PRRs) (DHX58), and IFN-stimulated genes (ISG15, Mx, STAT1, HERC5, IFI44, IFIT-1, NUP133, and TRIM21)." (PMID 30065724, 2018).
viral infection (continued). "The absence of IFI44 may reduce excessive inflammatory responses, which may have a protective role in pathological conditions such as viral infections." (PMID 40390102, 2025).
COVID-19 (17 papers, 2020 to 2025). A disease caused by infection with severe acute respiratory syndrome coronavirus 2. "The identification of DEGs such as OAS1, APOBEC3A, and IFI44, as well as genes associated with immune responses, highlights the robust activation of antiviral pathways during COVID-19." (PMID 41168347, 2025). "A similar result most probably is exerted by an overexpression of IFI44 in COVID-19 patients." (PMID 41168347, 2025). "Interestingly, the listed genes reported as potent markers of critical illness in COVID-19 (CCL2, MMP8, IFI44, LCN2, SAA1) were identified by us as key regulators of both murine ALI and COVID-19-associated ARDS in human with the highest scores of degree centrality." (PMID 34807957, 2021). "OAS1, OAS2, OAS3, IFIT1, IFIT3, IFI44, IFI44L and IFITM1: Current COVID-19 genetic studies incline to analyze those genes together." (PMID 34109284, 2021). "For the remaining five hub genes (TYMS, CDCA2, TOP2A, RRM2 and IFI44), there are no studies reporting their role in COVID-19 or pSS, which emphasizes its importance in future research." (PMID 35958619, 2022). "IFI44, OAS1, IFI44L, ISG15, and HERC5 are the five hub genes shared by RA, COVID-19, and SAB." (PMID 36189314, 2022). "An additional 8 targets (CXCL6, IFI44, IFI44L, RSAD2, S100A8, SPRR2A, SYNE1, XAF1) are associated with COVID-19 pathogenesis, but do not have therapies targeting them available for potential repurposing." (PMID 34582497, 2021).
lupus (10 papers, 2010 to 2025). "IFI44 has also been implicated as a biomarker in several immune disorders, including lupus, Sjögren's syndrome and immune cell infiltration and psoriasis." (PMID 39609844, 2024). "IFI44 is an interferon-stimulated gene (ISG) induced by type I interferons, and it has diagnostic value in autoimmune diseases such as systemic lupus erythematosus and primary Sjögren’s syndrome." (PMID 39958336, 2025). "Because ISG expression reflects serum IFN-I levels, we compared surface CD64 levels on monocytes with the transcript levels of three ISGs (MX1, IFI44, and Ly6E) in PBMCs from lupus patients (n = 108)." (PMID 20478071, 2010). "Many genes contained in the Hallmark IFN-α response and Hallmark TNF-α signaling pathways, including IFI27, IFI44, RELB, KLF6, and CD83, had significantly higher expression in lupus: We verified transcriptional changes in the naive compartment by quantitative PCR (qPCR)." (PMID 39688922, 2024). "Differentially methylated genes between African American and European American lupus patients include type I IFN–response genes such as IRF7 and IFI44, and genes related to the NF-κB pathway." (PMID 33108347, 2020). "An example of this is the IFI44 locus, which has many peak-gene linkages in lupus cells and not in healthy cells." (PMID 39688922, 2024). "In terms of epigenetics, IFI44 and IFIT3 were hypomethylated in comparisons between lupus patients and non-lupus subjects." (PMID 34760904, 2021).
influenza (8 papers, 2011 to 2024). An acute viral infection of the respiratory tract, occurring in isolated cases, in epidemics, or in pandemics; it is caused by serologically different strains of viruses (influenzaviruses) designated A, B, and C, has a 3-day incubation period, and usually lasts for 3 to 10 days. "In influenza patients, the interferon pathway-related genes IFI44, IFI6, IFIH1, STAT1, and GBP1 also showed overexpression, while no obvious interferon transcriptional signature was observed in AECOPD and CAP." (PMID 36059536, 2022). "The present work investigated the role of IFIT1–3 and IFI44 proteins in the cross-immunity effect observed between influenza and RSV." (PMID 33081322, 2020). "Furthermore, as IFIT1–3 and IFI44 were upregulated by influenza A, we hypothesized that they could be key players in RSV growth inhibition by influenza A." (PMID 33081322, 2020). "The influenza group’s validation experiment showed significant differences in all six genes (IFI44L, IFI44, RSAD2, IFIT3, EIF2AK2, and IFI27)." (PMID 38601162, 2024). "Their influenza classifier genes showed mostly IFN regulated genes, several of which (Ifi44, G1p2, Oas1, Zbp1) showed overlap with our signature." (PMID 21731757, 2011).
autoimmune disease (6 papers, 2020 to 2025). A disorder resulting from loss of function or tissue destruction of an organ or multiple organs, arising from humoral or cellular immune responses of the individual to their own tissue constituents. "Secondly, we need further experiments to verify our findings, such as validating in a larger scale and rigorous trial, evaluating the expression of the other biomarkers we identified, and comparing the expression of IFI44 in various autoimmune diseases." (PMID 35495164, 2022). "In the past years, researches have shown that IFI44 is one of the significant participants in immune response in autoimmune disease, HIV, and hepatitis diseases." (PMID 33123469, 2020). "Interferon-induced protein 44 (IFI44) containing a guanosine-5′-triphosphate (GTP) binding domain was reported to play a significant role in the immune response to autoimmune disease." (PMID 33123469, 2020). "IFI44 is a type I IFN signature gene, which may participate in the pathogenesis of autoimmune diseases." (PMID 39136821, 2024). "Both IFI44 and IFIT3 are type I IFN signature genes, which may contribute to the pathogenesis of autoimmune diseases." (PMID 34760904, 2021).
breast carcinoma (5 papers, 2018 to 2023). "In breast cancer, reduced expression of IFI44 in lymphocytes exacerbates cancer-associated immune dysfunction." (PMID 31703415, 2019). "For instance, IFIT3 and IFI44 mRNA were highly expressed in the invasive human breast cancer cell line MDAMB231, while their expression was low in the non-invasive MDAMB453." (PMID 36882786, 2023). "In addition, the down-regulated IFI44 in lymphocytes of breast cancer leads to immune dysfunction." (PMID 33101364, 2020). "(ii) In breast cancer, IRDS expression measured suggests seven genes (STAT1; MX1; ISG15; OAS1; IFIT1; IFIT3; and IFI44, interferon induced protein 44) whose cancers are resistant to therapies." (PMID 33922087, 2021). "Treatment of other breast cancer cells SKBR3 and BT474 by compound KDM5-C70 also induced expression of OAS2, IFI44L, and IFI44, but to a lesser extent." (PMID 30080846, 2018).
melanoma (5 papers, 2011 to 2023). A malignant, usually aggressive tumor composed of atypical, neoplastic melanocytes. "IFI-44 was found up-regulated in the peripheral blood and minor salivary glands of SS patients and displays an anti-proliferative activity in human melanoma cell lines." (PMID 30374345, 2018). "qPCR analysis of endogenous gene expression in mouse melanoma cells with Imp1-3 gene knockouts (no cytokine’s treatment) showed an increase of ISGs levels (e.g., Rig-1, Ifi44, Irf7/9, Oas2)." (PMID 37503349, 2023). "In addition, IFI44 inhibits cAMP-mediated signalling downstream of ERK via depletion of intracellular GTP, resulting in arrest of cell division in melanoma." (PMID 31703415, 2019).
lupus nephritis (4 papers, 2022 to 2025). Glomerulonephritis in the context of systemic lupus erythematosus. "This approach allows us to not only confirm IFI44’s presence but also to evaluate its differential expression in various kidney compartments and its direct association with the pathological features of lupus nephritis." (PMID 40101924, 2025). "In our study, IFI44 expression in lupus nephritis (LN) patients predominantly localized to the nucleus, contrasting with its distribution in both the nucleus and cytoplasm in Minimal Change Disease (MCD) and normal controls (NC)." (PMID 40101924, 2025). "have explored the role of IFI44 as a potential biomarker in lupus nephritis, our research extends these findings by specifically correlating IFI44 expression with disease severity through detailed immunohistochemical analysis." (PMID 40101924, 2025). "This correlation underscores the potential of IFI44 as a marker for disease severity in lupus nephritis, suggesting that elevated renal expression of IFI44 could be indicative of an aggressive disease phenotype." (PMID 40101924, 2025). "By linking IFI44 expression to disease severity, our study provides critical insights that could influence the clinical management of lupus nephritis." (PMID 40101924, 2025). "Results showed that compared to that in healthy controls, the expression of IFI44 in SLE patients’ PBMCs was significantly higher no matter whether lupus nephritis (LN) was present." (PMID 35495164, 2022).
gastric cancer (3 papers, 2019 to 2020). A primary or metastatic malignant neoplasm involving the stomach. "We also assessed the survival associations of IFI44 and IFI30 expressions using the gene expression data of gastric cancer patients registered in the Gene Expression Omnibus (GEO)." (PMID 33257699, 2020). "For HER2+ gastric cancer, the high expression of VIM, IFI44, IFI44L, IFIT2, IFIT3, ISG15, OAS1, or OASL was associated with worse overall survival (P < 0.05)." (PMID 31949544, 2019). "In contrast, the protein of IFI44 showed lower expression in gastric cancer." (PMID 33123469, 2020). "For all gastric cancer cases, our results showed that high ERBB2 expression was associated with the worse overall survival of GC patients, VIM, IFI44, IFIT2, and MX1 showed similar associations (P < 0.05)." (PMID 31949544, 2019).